PTP4A2 (protein tyrosine phosphatase 4A2)
Description:
Protein tyrosine phosphatase which stimulates progression from G1 into S phase during mitosis. Promotes tumors. Inhibits geranylgeranyl transferase type II activity by blocking the association between RABGGTA and RABGGTB.
Synonyms: PRL-2; PRL2; PTPCAAX2; HU-PP-1; OV-1; ptp-IV1a; HH13; HH7-2; PTP4A; ptp-IV1b
Tractability: Small molecule: a structure with a bound ligand is known; a high-quality ligand is known; it belongs to a druggable protein family. Antibody: UniProt places it where antibodies can reach, with medium confidence; its Gene Ontology location is reachable by antibodies, with medium confidence. PROTAC: ubiquitination databases record sites on it; its protein half-life has been measured; a small molecule that binds it is known.
Target class: Tyrosine protein phosphatase; Enzyme; Phosphatase; Protein Phosphatase
Gene: Protein-coding gene on chromosome 1 (31,906,421 to 31,944,856, reverse strand). Ensembl gene ENSG00000184007.
Subcellular location: Cell membrane; Early endosome; Cytoplasm
Pathways (Reactome):
Metabolism of proteins: RAB geranylgeranylation
Gene Ontology:
Molecular function: protein binding; protein tyrosine phosphatase activity; enzyme inhibitor activity
Cellular component: cytoplasm; cytosol; nucleus; early endosome; plasma membrane
Genetic constraint (gnomAD): Loss-of-function variants: 0 observed, 9.69 expected, observed/expected ratio (o/e) 0, 90% interval 0 to 0.31. That is too few expected variants to judge how well the gene tolerates losing a copy. Missense variants: 38 observed, 86.71 expected, observed/expected ratio (o/e) 0.44, 90% interval 0.34 to 0.57. Synonymous variants: 28 observed, 29.22 expected, observed/expected ratio (o/e) 0.96, 90% interval 0.71 to 1.31.
Homologues: Orthologues: chimpanzee PTP4A2 (100% identical), macaque PTP4A2 (100% identical), mouse Ptp4a2 (100% identical), rat Ptp4a2 (100% identical), dog PTP4A2 (99% identical), rabbit PTP4A2 (99% identical), tropical clawed frog ptp4a2 (94% identical), zebrafish ptp4a2a (84% identical), zebrafish ptp4a2b (84% identical), pig PTP4A2 (83% identical), Drosophila melanogaster PRL-1 (56% identical), Caenorhabditis elegans ptp-4A2 (54% identical). Paralogues in human: PTP4A1 (89% identical), PTP4A3 (78% identical), CDC14A (33% identical), CDC14B (31% identical), CDC14C (30% identical), PTPDC1 (28% identical), CDKN3 (25% identical), PALD1 (14% identical).
Diseases named in the same sentence as PTP4A2 in open-access papers:
PTP4A2 is named in the same sentence as 57 diseases in open-access papers, as found by Europe PMC text mining. Sharing a sentence is not in itself a finding about the gene and the disease. The quoted sentences say what the papers report.
breast carcinoma (18 papers, 2006 to 2025). "PTP4A2 (protein tyrosine phosphatase 4A2) is associated with the overall and disease-free survival of breast cancer." (PMID 35280808, 2022). "Although previous studies have already demonstrated the oncogenic role of PTP4A2 in mouse models including breast cancer xenograft and T-cell leukemia, their results correlated with their in vitro observations." (PMID 38904264, 2024). "Similar findings have been reported in the prognostic impact of PTP4A2 on other human cancers, such as human breast cancer and colony cancer." (PMID 29100406, 2017). "Microarray and qPCR expression of PTP4A2 expression was elevated in both estrogen receptor (ER)-positive and progestin receptor (PR)-positive breast cancer biopsies compared to ER-negative or PR-negative biopsies." (PMID 24633017, 2014). "PTP4A2, upregulated in breast cancer, promotes cancer progression through various pathways." (PMID 41378310, 2025). "Furthermore PTP4A2/PRL2 expression has been linked to signaling by the sex hormones estrogen and progesterone in breast cancer." (PMID 24633017, 2014). "In breast cancer models, polypropylene increased AP2M1, PTP4A2, and TMBIM6 while reducing FTH1, a pattern consistent with enhanced trafficking/ER-stress signaling and diminished iron-mediated tumor suppressive functions." (PMID 41378310, 2025). "For breast cancer, miR-483-3p and miR-138-5p showed favorable predictions against ABCB1/PTP4A2 and TMBIM6, respectively, while miR-365 and miR-331-3p mapped to ABCG2/AP2M1." (PMID 41378310, 2025). "In particular, high PTP4A2 expression was found to be related with shorter OS and DFS in breast cancer patients." (PMID 29100406, 2017). "Other genes affected by MPs in breast cancer include FTH1, PTP4A2, and TMBIM6." (PMID 41378310, 2025). "We also found that the gene expression of TMBIM6, AP2M1, and PTP4A2, which are correlated with cancer progression and the cell cycle, was significantly increased by PPMP incubation in MDA-MB-231 human breast cancer cells, suggesting that PPMPs regulate the transcriptional activity of cancer cells." (PMID 37069244, 2023). "It was postulated that the PTP4A2 gene is an oncogene which could be responsible for enhancing tumourigenesis and progression in NPC, similar to other types of human cancer such as breast cancer, colon cancer, and lung cancer." (PMID 35565251, 2022).
colon cancer (3 papers, 2013 to 2022). "Interestingly, the gene expression levels of Ptp4a1 and Ptp4a2 were both downregulated 64% and 36% (p<0.0001 and p<0.05), respectively, in colon tumors relative to normal tissue." (PMID 23555575, 2013).
glioma (2 papers, 2022 to 2024). A benign or malignant brain and spinal cord tumor that arises from glial cells (astrocytes, oligodendrocytes, ependymal cells). "High levels of PTP4A2 are associated with poor outcomes in patients with glioma and in mouse models." (PMID 38904264, 2024). "We also show that PTP4A2 is associated with a poor prognosis in gliomas, and its expression correlates with GBM aggressiveness." (PMID 38904264, 2024). "Moreover, a high expression of PTP4A2 was associated with poor prognosis for both GBM and IDH-mutant gliomas." (PMID 38904264, 2024). "We found that the PTP4As are upregulated in both isocitrate dehydrogenase (IDH)–mutant gliomas and GBM (IDH wild-type) compared with normal brain tissue with PTP4A2 being the most expressed." (PMID 38904264, 2024).
allergic disease (1 paper, 2025). An immune response that occurs following re-exposure to an innocuous antigen, and that requires the presence of existing antibodies against that antigen. "Although PRL2 is highly expressed in MCs (expression pattern of Ptp4a2 in MCs from BioGPS database) any potential role it might play in allergic disease remains unclear." (PMID 40258807, 2025).
colorectal cancer (1 paper, 2017). A primary or metastatic malignant neoplasm that affects the colon or rectum. "Of note, we reported previously PTP4A2 was up-regulated in colorectal cancer (CRC) and associated with CRC metastasis." (PMID 29100406, 2017). "We previously discovered that PTP4A2 could activate AKT/GSK3β/β-catenin pathways to induce epithelial-to-mesenchymal transition (EMT) during colorectal cancer metastasis." (PMID 29100406, 2017).
diabetes (1 paper, 2016). "Other genes in the SB network related to diabetes are PTP4A2, IQGAP2, and SOCS4." (PMID 26830357, 2016).
fibrosis (1 paper, 2017). the formation of excess fibrous connective tissue in an organ or tissue in a reparative or reactive process. "PTP4A1 and its close homolog PTP4A2 are critical promoters of TGFβ signaling in primary dermal fibroblasts and of bleomycin-induced fibrosis in vivo." (PMID 29057934, 2017). "PTP4A2 similarly promotes pro-fibrotic TGFβ signaling in NHDF lines and bleomycin-induced fibrosis in vivo." (PMID 29057934, 2017).
Insulin resistance (1 paper, 2005). Increased resistance towards insulin, that is, diminished effectiveness of insulin in reducing blood glucose levels. "Therefore if PTP4a2 also negatively regulates insulin signaling, its significant downregulation (p < 0.01) following 10 weeks of high-fat feeding may be a physiological adaptation that protects hepatocytes against insulin resistance, which is normalized by fasting/ weight reduction." (PMID 15985155, 2005).
major depressive disorder (1 paper, 2022). An episode of depression lasting two or more weeks without an intervening episode of mania. "Furthermore, the most significant proteins for suicide in the WGCNA analysis included CAPNS1 (Calpain Small Subunit 1), which is suggested to play a neuroprotective role, and CSNK2B and PTP4A2, implicated as biomarkers for psychiatric disorders such as major depressive disorder and schizophrenia." (PMID 35383147, 2022).
nasopharyngeal carcinoma (1 paper, 2017). A carcinoma arising from the nasopharyngeal epithelium. "In two large cohorts of nasopharyngeal carcinoma samples, overexpression of PTP4A2 protein was observed in 40.6% (108/266) and 50.7%(102/201) of NPC tissues, respectively." (PMID 29100406, 2017). "However, the level of PTP4A2 expression and its prognostic significance in nasopharyngeal carcinoma (NPC) remains unknown." (PMID 29100406, 2017).
cancer (32 papers, 2009 to 2025). A tumor composed of atypical neoplastic, often pleomorphic cells that invade other tissues. "The PTP4A2 phosphatase has previously been linked to multiple cancer types, and we now report that its oncogenic functions also contribute to GBM progression." (PMID 38904264, 2024). "Protein tyrosine phosphatase 4A2 (PTP4A2) has been implicated as an oncogenic protein in several human cancers." (PMID 29100406, 2017). "Phosphatase of regenerating liver 2 (also known as PTP4A2) has been linked to cancer progression." (PMID 38904264, 2024). "PTP4A3 is the most frequently overexpressed PTP4A phosphatase in different cancer types, although some cancers also co‐express PTP4A1 and/or PTP4A2." (PMID 40657934, 2025). "Phosphatases of regenerating liver (PRLs) PRL-1, PRL-2 and PRL-3, encoded by the genes PTP4A1, PTP4A2 and PTP4A3, respectively, are dual-specific phosphatases, which promote proliferation, migration and invasion of cancer cells." (PMID 32260565, 2020). "The potential function of PTP4A2 in cancer progression have been explored in recently investigations." (PMID 29100406, 2017). "Recently, accumulating studies showed that up-regulated expression of PTP4A2 correlated significantly with cancer progression in several types of malignancies." (PMID 29100406, 2017). "While this observation was unexpected based on the reports that both PTP4A1 and PTP4A2 promote ERK signaling in cancer cells, it does support the possibility that, in NHDF lines, only PTP4A1 controls TGFβ signaling through the ERK pathway." (PMID 29057934, 2017). "Phosphatases of regenerating liver (PRLs), PRL-1, PRL-2, and PRL-3, constitute a group of three dual specificity phosphatases encoded by the genes PTP4A1, PTP4A2, and PTP4A3, respectively, and whose high expression is associated to cancer progression." (PMID 33425892, 2020). "Collectively, these data suggest that PTP4A2 expression may function as on oncogene of malignant transformation in human cancers." (PMID 29100406, 2017). "However, SUMF2, PTP4A2, and IMP4 are associated with other types of carcinomas." (PMID 41263940, 2025). "All these study illustrated that the function of PTP4A2 in human cancer might be tissue-specific." (PMID 29100406, 2017). "However, few studies have reported the specific functions of PTP4A2 in human cancer types." (PMID 29100406, 2017). "Of note, Li and colleagues have recently reported that high PTP4A2 expression downregulated the PTEN level by dephosphorylation, suggesting that PTP4A2 supports oncogenic propensity of PTEN deletion in cancer." (PMID 38904264, 2024). "Phosphatases of regenerating liver (PRLs) comprise a group of 3 highly homologous small DSPs (PRL-1/PTP4A1, PRL-2/PTP4A2, and PRL-3/PTP4A3) overexpressed in several cancer types, including hematological malignancies." (PMID 30515156, 2018). "Although in present study, we identified the correlation of PTP4A2 expression in cancer and NPC patients’ survival, more works are needed in the future study to elucidate the mechanisms by which PTP4A2 is involved in the development and progression of NPC." (PMID 29100406, 2017). "Cancers with scores above the obtained cut-off value were considered to have high PTP4A2 expression, which led to the greatest number of cancers correctly classified, based on having or not having the clinical outcome." (PMID 29100406, 2017). "Differentially expressed Ptp4a2 (protein tyrosine phosphatase 4a2, also known as protein-tyrosine phosphatase of regenerating liver 2 or PRL-2) is a widely expressed gene and is found overexpressed in some cancers." (PMID 23934554, 2013).
tumor (23 papers, 2013 to 2026). "Protein tyrosine phosphatase 4A2 (PTP4A2) is a protein that has been specifically implicated in tumor progression and associated tumor growth." (PMID 41302034, 2025). "In this study, qRT-PCR was used to detect the expression of circPTP4A2 (circular RNA PTP4A2) in tumor and adjacent normal tissues from 50 NSCLC patients." (PMID 42098805, 2026). "Nevertheless, increased levels of PTP4A2 in tumor cells enhanced tumor growth and impaired mouse survival." (PMID 38904264, 2024). "We conducted orthotopic implantation of PTP4A2-KO, control (Ctrl), and PTP4A2-OE P3 spheroids in which tumor development was monitored for 2 to 3 months." (PMID 38904264, 2024). "Using a GBM orthotopic xenograft model, we show that PTP4A2 overexpression promotes tumor growth and reduces mouse survival." (PMID 38904264, 2024). "Together, these in vitro results suggest that the effects of PTP4A2 on tumor growth most likely involve the TME present in our in vivo xenograft model." (PMID 38904264, 2024). "To further explore the effects of PTP4A2 deletion on the tumor microenvironment, we used a syngeneic GBM mouse model." (PMID 38904264, 2024). "Monitoring tumor growth by bioluminescence showed that PTP4A2-KO tumors tend to grow slower than Ctrl tumors." (PMID 38904264, 2024). "This was also confirmed at the histologic level with the PTP4A2-OE tumor area covering more than 50% of the brain section area at its maximal size." (PMID 38904264, 2024). "In an immunocompetent host, PTP4A2 depletion significantly impacted tumor growth and rewired the TME by affecting immunity and the vasculature." (PMID 38904264, 2024). "Expression analysis by qPCR, using human-specific primers, showed a significant increase in the expression of some chemoattractant factors (i.e., CCL2 and CSF1) of the cell-cycle inhibitor P21 in the tumor cells of PTP4A2-KO xenografts." (PMID 38904264, 2024). "Using a syngeneic GBM model, we show that depletion of PTP4A2 reduces tumor growth and induces a shift in the tumor microenvironment (TME) toward an immunosuppressive state." (PMID 38904264, 2024). "Deleting PTP4A2 reduced tumor growth and increased apoptosis in vivo, and overexpressing PTP4A2 promoted tumor growth." (PMID 38904264, 2024). "Finally, the decrease in PTP4A2 levels in GBM cells affects the tumor microenvironment (TME) by increasing proinflammatory signals." (PMID 38904264, 2024). "In addition to the key role of the TME in PTP4A2 effects, heterogeneity most probably influences the regulation of PTP4A2 differentially in distinct areas of the tumor." (PMID 38904264, 2024). "PTP4A2 has been reported to influence tumor progression and stem cell self-renewal." (PMID 33138667, 2020). "Another protein that was significantly upregulated following PXDN knockdown was protein tyrosine phosphatase type IVA 2/ phosphatase of regenerating liver (PTP4A2/PRL-2); this is a prenylated protein tyrosine phosphatase with oncogenic activity that has been proposed to drive tumor metastasis." (PMID 31234468, 2019). "PTP4A2 depletion increases apoptosis and proinflammatory signals in GBM xenograft models, significantly impacts tumor growth, and rewires the TME in an immunocompetent host." (PMID 38904264, 2024). "PTP4A1, PTP4A2, and PTP4P3 are three closely related small PTPs which drawn attention to us about their functions in tumor cell proliferation, including promotion of tumor migration, invasion, and metastasis." (PMID 29100406, 2017). "In this study, Western blotting (WB), quantitative real-time PCR (qT-PCR) and immunohischemistry (IHC) was applied to evaluated the expression levels of PTP4A2 in NPC cell lines and tumor tissues combining two independent cohorts." (PMID 29100406, 2017). "This analysis showed that the modulation of PTP4A2 expression did not affect tumor cell proliferation." (PMID 38904264, 2024). "Although mouse survival was not significantly affected by PTP4A2-KO, it was reduced in PTP4A2-OE tumor–bearing mice." (PMID 38904264, 2024).
tumor (continued). "Markers for total macrophages/microglia such as Adgre (F4/80) or Aif1 (IBA1) were not differentially expressed, suggesting that PTP4A2 expression did not affect macrophage accumulation inside the tumor." (PMID 38904264, 2024). "In our study, PTP4A2 depletion or OE had mostly no consequence on in vitro cell proliferation/viability but a significant effect on tumor growth in the orthotopic GBM xenograft mouse model." (PMID 38904264, 2024). "Consistently, IHC staining showed that PTP4A2 is up-regulated in tumor tissues compared with the corresponding adjacent non-neoplastic nasopharyngeal tissues (ANTs)." (PMID 29100406, 2017). "The lack of functional antibodies for PTP4A1 and PTP4A2 precluded evaluating the tumor protein levels for these family members." (PMID 23555575, 2013).
PTP4A2 also shares sentences with these, for which no sentence is quoted: lung carcinoma (6 papers); infection (3); ovarian carcinoma (3); leukaemia (2); acute myeloid leukemia (1); allergies (1); Anxiety (1); bacterial infection (1); breast tumors (1); colorectal (1); congenital heart disease (1); degenerative diseases (1); gastric cancer (1); genetic disease (1); glioblastoma (1); hematological malignancies (1); Hepatoma (1); infectious disease (1); ischemia (1); kidney diseases (1); leiomyosarcoma (1); listeria infection (1); lung adenocarcinoma (1); lung diseases (1); lymphoma (1); malaria (1); neuroblastoma (1); non-small cell lung carcinoma (1); papillary renal cell carcinoma (1); Parkinson's (1).
A further 15 diseases each share a sentence with PTP4A2 in 1 paper.